INS (insulin)
Diseases named in the same sentence as INS in open-access papers (continued):
Sharing a sentence is not in itself a finding about the gene and the disease.
type 2 diabetes (continued). "This study aimed to explore healthcare professionals’ views on barriers to starting insulin therapy in people with type 2 diabetes." (PMID 22469132, 2012). "We measured Ucp2 expression as this has been proposed to be major factor in obesity, beta cell dysfunction, and type 2 diabetes, negatively regulating insulin secretion." (PMID 22808281, 2012). "In individuals with type 2 diabetes or pre-diabetes, hyperglycemia is due in part to decreased responsiveness of tissues to the hormone insulin, a phenomenon known as insulin resistance." (PMID 23056469, 2012). "Our pattern of SNP main and interactive results resemble the patterns seen in another recent application of the same JMA method to incorporate the interaction with body mass index (BMI) into GWAS of type 2 diabetes traits (fasting insulin and blood glucose)." (PMID 23284291, 2012). "Until recently, the mainstay oral medications to improve insulin action in type-2 diabetes have been biguanides (e.g.metformin) and thiazolidinediones (TZDs)." (PMID 22860063, 2012). "There is little research on what barriers the multi-ethnic Malaysian patients with type 2 diabetes face when deciding to initiate insulin." (PMID 22469132, 2012). "Over time, beta cell function further declines in most people with type 2 diabetes, resulting in the eventual failure of oral medications and the necessity of insulin therapy." (PMID 22253604, 2012). "Several studies have provided evidence for defects in the insulin signaling in human skeletal muscle from obese and type 2 diabetes subjects using in vitro and in vivo approaches." (PMID 22470480, 2012). "Affectation of GABA receptors in pancreatic islets is partly responsible for decreased insulin release in type 2 diabetes, and GABA supplementation has been reported to increase insulin release." (PMID 23304216, 2012). "Insulin secretion in response to amino acids is interesting in terms of treatment of type-2 diabetes." (PMID 22647249, 2012). "This is of interest, since it has been recently shown that daily injections of osteocalcin can improve glucose tolerance by increasing insulin secretion and beta cell mass and thus prevent the development of type 2 diabetes in experimental animals." (PMID 22844418, 2012). "Type 2 diabetes is a metabolic disorder characterized by the inability of beta-cells to secrete enough insulin to maintain glucose homeostasis." (PMID 22808281, 2012). "From this perspective, the insulin sensitizing anti-diabetic agent pioglitazone ameliorates NASH pathology in patients with type 2 diabetes." (PMID 23028442, 2012). "Synthetic PPARγ agonists, the thiazolidinediones (TZDs), are used in type II diabetes therapy as insulin sensitizers to overcome insulin resistance in target tissues." (PMID 23213321, 2012). "Adiponectin is another circulating adipokine that correlates well with whole-body insulin sensitivity and is decreased in subjects with type 2 diabetes." (PMID 23146593, 2012). "The prescription of insulin in type 2 diabetes is mandatory in case of ketoacidosis, or hypeglycemia associated with loss." (PMID 23209929, 2012). "The hyperglycemia is caused as a consequence of a deficiency in insulin in type 1 diabetes (T1D), and is a feature of late type 2 diabetes (T2D) along with insulin resistance." (PMID 22546713, 2012). "Recently, ER stress has been known to reduce the insulin sensitivity of the liver and lead to type 2 diabetes." (PMID 23247284, 2012). "Endurance exercise training performed three times weekly markedly improved whole body insulin sensitivity and normalised muscular glucose transport/phosphorylation within 6 weeks in first-degree relatives of patients with type 2 diabetes." (PMID 22391950, 2012). "Insulin is recommended as an appropriate treatment in type 2 diabetes patients with suboptimal glycemic control; however, its initiation is often delayed." (PMID 22719830, 2012).
type 2 diabetes (continued). "If milk insulin concentration does reflect or mirror blood insulin concentrations, then the elevated insulin levels seen would typically represent a woman with undiagnosed, untreated type 2 diabetes." (PMID 22500167, 2012). "Treatment with 70% NPH insulin/30% regular insulin has been shown to reduce TC and TGs in patients with type 2 diabetes." (PMID 22081557, 2012). "Type 2 diabetes is a long term metabolic disorder where the body becomes resistant to the effect of insulin, a hormone that regulates sugar absorption." (PMID 23675267, 2012). "Dose similarities between insulin detemir and insulin glargine were seen in type 2 diabetes patients when administered once daily." (PMID 23009558, 2012). "The therapeutic effects of genipin on type 2 diabetes were presumed to be attributed to its role on stimulating insulin secretion and thereafter modulating the blood glucose level." (PMID 22848482, 2012). "Type 2 diabetes genes have appeared to be more selective in their influence on organ dysfunctions, with defective pancreatic insulin secretion being the most important." (PMID 22643933, 2012). "In patients with both Type 1 and Type 2 diabetes endogenous insulin secretion falls with time which changes treatment requirements, however direct measurement of endogenous insulin secretion is rarely performed." (PMID 22681724, 2012). "Type 2 diabetes is a progressive disease that requires stepwise additions of non-insulin and insulin therapies to meet recommended glycaemic goals." (PMID 23061886, 2012). "IDE plays essential role in insulin homeostasis, implicating a close relationship between AD and type II diabetes (DM2)." (PMID 23210692, 2012). "Insulin is the life-saving hormone for people suffering from type 1 and at times type 2 diabetes (see what follows)." (PMID 22567309, 2012). "The peroxisome proliferator-activated receptor-gamma has been the focus of intense research during the past decade because ligands for this receptor have emerged as potent insulin sensitizers used in the treatment of type II diabetes." (PMID 23213321, 2012). "Type 2 diabetes (T2D) is a common and complex disease characterized by a state of hyperglycemia resulting from defects in insulin action combined with dysfunction of the pancreatic β-cell." (PMID 22325233, 2012). "• The first case involved patients with diabetes mellitus type II, treated with insulin for 30 years, with macro vascular disease with symptoms of intermittent claudication." (PMID 22272570, 2012). "One common feature of obesity and type 2 diabetes is hyperinsulinemia leading to insulin desensitization." (PMID 22654904, 2012). "Other studies demonstrated that PTPMeg2 regulates insulin production, beta cell growth or insulin signaling by reducing insulin receptor dephosphorylation in type II diabetes." (PMID 22394684, 2012). "A 43-year-old man with type 2 diabetes, opposed to insulin use and poorly responsive to oral agents added sequentially over 6 years, was placed on 40 mg omeprazole twice daily." (PMID 22937295, 2012). "An unanswered question arises: Is there a fundamental relationship between diminished glucose effectiveness and diminished insulin sensitivity in people in the prediabetic phase and people with type 2 diabetes, and if so, what is that relationship?" (PMID 22698081, 2012). "The only long-term comparison of insulin with other drugs for type 2 diabetes reporting data on the incidence of malignancies is the ORIGIN trial." (PMID 23209929, 2012). "It is recognized, that in the pathophysiology of type 2 diabetes both disturbances in insulin action (liver and muscle) and in insulin secretion are early events with additional factors such as age itself." (PMID 22403629, 2012). "This study used Taiwan's National Health Insurance claims database to investigate the relationship between type 2 diabetes, glucose-lowering therapy with either metformin, sulphonylureas, or insulin alone, and cancer in the Taiwanese." (PMID 22719752, 2012).
type 2 diabetes (continued). "This is consistent with previous research in non insulin treated Type 2 diabetes has shown that those with low insulin secretion have higher glucose increment after oral glucose tolerance test and higher glycaemic variability." (PMID 22681724, 2012). "It stimulates insulin biosynthesis, inhibits glucagon secretion, slows gastric emptying and reduces appetite, making it an ideal therapeutic target for patients with type 2 diabetes." (PMID 22613296, 2012). "Type 2 diabetes (T2D) is characterized by hyperglycaemia resulting from impaired insulin secretion and/or impaired insulin action in peripheral tissues." (PMID 22577380, 2012). "Eight observational studies also examined insulin–exenatide combination therapy in patients with type 2 diabetes." (PMID 23061886, 2012). "Type 2 diabetes is characterized by insulin resistance of target cells, mainly muscle and fat cells." (PMID 23164557, 2012). "Combined endurance and resistance exercise for 12 weeks also normalised muscular mitochondrial density and capacity in individuals with type 2 diabetes, although insulin sensitivity remained reduced." (PMID 22391950, 2012). "In a combined high-fat diet and STZ-induced type 2 diabetic animal model, better glucose tolerance and enhanced serum insulin concentration were observed in ginger-treated diabetic rats." (PMID 23243452, 2012). "The authors examined three different groups, each comprising 15 middle-aged overweight to obese males: impaired glucose tolerance, type 2 diabetes on oral glucose-lowering agents and type 2 diabetes on insulin." (PMID 22391950, 2012). "Although exercise training has been shown to improve insulin resistance and glucose metabolism in obese patients with type 2 diabetes, most effects are observed after longer exercise programs." (PMID 22647230, 2012). "Clinical trials in type 2 diabetes have reported less weight increase and less reduction in HbA1c but fewer hypoglycaemic episodes during treatment with basal insulin." (PMID 23166795, 2012). "In case of type II diabetes, there is normal production of insulin hormone but the body cells are resistant to insulin, a condition in which cells fail to use insulin properly, or sometimes combined with an absolute insulin deficiency." (PMID 22611498, 2012). "Type 1 diabetes was defined by insulin prescriptions with at most one oral hypoglycemic prescription; other cases were considered type 2 diabetes." (PMID 22920280, 2012). "Insulin resistant Caucasians develop hyperinsulinemia to maintain glucose intolerance which delays the onset of type 2 diabetes." (PMID 23270397, 2012). "These physiologic alterations are thought to contribute to insulin resistance and beta islet cell dysfunction, leading to development of type 2 diabetes." (PMID 23181626, 2012). "Our study does offer a broad perspective and more insight into the influencing factors and the relationship between them among patients with type 1 and insulin-treated patients with type 2 diabetes." (PMID 22397638, 2012). "Type 2 diabetes mellitus (T2DM) is characterized by insufficient insulin secretion and insulin resistance, such that the liver lacks the ability to regulate glycolysis and gluconeogenesis." (PMID 23118787, 2012). "In people with insulin-treated type 2 diabetes, recall of severe hypoglycaemia is similarly robust over a period of one year but the reliability of recall of mild hypoglycaemia has not been examined and is unlikely to be preserved." (PMID 23075070, 2012). "Chromium is thought to play a key role in normal carbohydrate metabolism by potentiating the action of insulin, leading to increase insulin sensitivity in type II diabetes and obesity." (PMID 22988520, 2012). "In the diabetic state, hyperglycemia per se and subsequent induction of oxidative stress decrease insulin biosynthesis and secretion, leading to the aggravation of Type 2 diabetes." (PMID 23202973, 2012).
type 2 diabetes (continued). "Sitagliptin has been shown, in several clinical studies to improve metabolic control in type 2 diabetes, both as monotherapy or in combination with metformin, sulfonylurea, thiazolidinediones or insulin." (PMID 23554750, 2012). "More recently, others have tried to overcome biases by comparing glargine to human insulin, while excluding other insulin analogs, or by including only individuals with type 2 diabetes." (PMID 22917080, 2012). "In our study of insulin treated patients with Type 1 and Type 2 diabetes postprandial hyperglycaemia is inversely related to endogenous insulin secretion." (PMID 22681724, 2012). "In type 1 diabetes, the immune system attacks the cells that make insulin; type II diabetes is also linked to inflammation, as chronic inflammation induces the release of TNF- α, which makes cells more resistant to insulin." (PMID 22690145, 2012). "Skeletal muscle is the primary site of insulin-dependent glucose disposal and resistance of skeletal muscle to insulin’s action is an early step in the development of type 2 diabetes." (PMID 23115649, 2012). "The decline in insulin action with age is thought to contribute to the high prevalence of impaired glucose tolerance and Type 2 diabetes among the elderly." (PMID 22675349, 2012). "At the same time, obese patients require more insulin to maintain blood glucose homeostasis – a state known as hyperinsulinemia, a condition that can evolve into type 2 diabetes." (PMID 23009606, 2012). "We also show for the first time that a key determinant of serum apelin levels is the basal disposition index, a surrogate measure of the two major defects in type 2 diabetes, defective insulin secretion and impaired insulin-sensitivity." (PMID 23227256, 2012). "Casein protein hydrolysate and leucine co-ingestion in patients with type 2 diabetes stimulated postprandial insulin secretion." (PMID 22891897, 2012). "We aimed to assess this in a mixed population of Type 1 and Type 2 diabetes with a wide spectrum of insulin secretion." (PMID 22681724, 2012). "A chronic inflammatory process underlies the failure of the beta-cells to secrete a sufficient amount of insulin in patients with type 2 diabetes." (PMID 22922276, 2012). "This study investigates patients' perspectives of SMBG and all relevant aspects influencing SMBG in patients with type 1 and insulin-treated type 2 diabetes." (PMID 22397638, 2012). "The type 2 diabetes is a complex disease characterized by decrease of insulin sensitivity and impaired insulin secretion." (PMID 22770114, 2012). "Type 2 diabetes is characterized by two major features, such as insulin resistance of the liver, adipose tissue and muscle, and impaired insulin secretion from pancreatic β-cells." (PMID 23247284, 2012). "This study also aimed to compare the levels of insulin in breast milk from mothers with type 2 diabetes and then investigate any relationship between blood glucose, milk insulin, glucose, c-peptide, and sodium content in breast milk in each of the groups." (PMID 22500167, 2012). "The levels of MIF, insulin, ghrelin, leptin, glucagon, resistin and adipsin are similar in type 2 diabetes and CHD patients whereas IL-1α, IL-2R, IL-12, IL-18, HGF, and PAI-1 are higher in CHD patients than in type 2 diabetes patients (with p-value <0.01)." (PMID 22745767, 2012). "The interesting and novel feature of our study is the use of state-of-art methods, instead of surrogate markers, to assess beta cell function and insulin sensitivity in a sample of patients with newly diagnosed type 2 diabetes." (PMID 22427875, 2012). "The healthy controls and patients with type 2 diabetes were divided into low (QL) and high (QH) muscle content of myostatin mRNA and the fasting glucose, insulin, HOMA2-IR, and plasma IL-6 levels were compared." (PMID 22615949, 2012).
type 2 diabetes (continued). "This study aimed to explore the views of Malaysian healthcare professionals (HCPs) on the strategies that would facilitate insulin initiation among patients with type 2 diabetes." (PMID 22545648, 2012). "The researchers are planning to conduct interviews with patients with type 2 diabetes who are considering insulin as part of a larger study." (PMID 22545648, 2012). "The model is able to describe metabolic dynamics of the glucose‐insulin regulatory system also for the pathological case of type 1 or type 2 diabetes." (PMID 23164557, 2012). "Evidence supporting this notion is consistent with clinical observations that α-cell insulin resistance exaggerates glucagon responses to stimuli in type 2 diabetic patients." (PMID 23316165, 2012). "To date, insulin remains the only therapy for type 1 diabetes, and the most effective glucose-lowering drug for type 2 diabetes." (PMID 23209929, 2012). "TZDs are a class of oral insulin-sensitizing agents, extensively used in the treatment of type 2 diabetes." (PMID 22808264, 2012). "An imbalance between insulin production and secretion, which is likely to occur in type 2 diabetes, induces autophagy to degrade accumulated insulin granules." (PMID 22474427, 2012). "Mitiglinide also improves postprandial hyperglycemia in type 2 diabetes patients via both an insulin-mediated indirect effect on the liver and a direct regulatory influence over hepatic glucose metabolism." (PMID 22748110, 2012). "People with self-reported type 1 diabetes (specifically those on insulin pump therapy) were over-represented, as were those using insulin among respondents with self-reported type 2 diabetes." (PMID 23110382, 2012). "Impaired insulin secretion together with insulin resistance is a key factor in the pathogenesis of type 2 diabetes mellitus." (PMID 23077502, 2012). "Patients with type 2 diabetes had higher fasting glucose (8.9 versus 5.1 mmol/L, P<0.001), plasma insulin (68.2 versus 47.2 pmol/L, P<0.002) and HOMA2-IR (1.6 versus 0.9, P<0.0001) when compared to controls." (PMID 22615949, 2012). "Women with type 2 diabetes in use of oral hypoglycemic agents are advised to change to insulin therapy." (PMID 22964143, 2012). "An interesting link between insulin and Aβ is that they both are IDE substrates, and the patients with type 2 diabetes have an increased risk of AD." (PMID 22719789, 2012). "This enhancement would be incomparable with the increase in the basal insulin secretion observed in type 2 diabetes with obesity." (PMID 22470529, 2012). "In an Asian type 2 diabetes population insufficiently controlled by basal insulin ± sulfonylurea, once-daily lixisenatide significantly improved glycaemic control, with a pronounced postprandial effect, and was well tolerated." (PMID 22564709, 2012). "We enumerated peripheral blood PPCs as Syto16+CD45−CD31−CD140b+ events by flow cytometry at baseline and after 3 and 6 months of glucose control by means of add-on basal insulin therapy on top of oral agents in 38 poorly controlled type 2 diabetic patients." (PMID 22474419, 2012). "Type 2 diabetes are characterized by hyperglycemia, insulin resistance and defects in insulin secretion, thus the patient with type 2 diabetes often suffer from symptoms of dyslipidemia, hypertension as well as obesity." (PMID 23119024, 2012). "Type II diabetes was also more prevalent among the individuals who were exposed to the famine in utero, marked by reduced glucose tolerance and raised insulin concentrations among middle-age individuals." (PMID 22970372, 2012). "Restoration and improvement of first-phase insulin secretion is an important target in the treatment of type 2 diabetes and is a major property of sulphonylureas which have been shown in some studies to almost double the first-phase insulin response." (PMID 22815837, 2012).